MARCOL (MARCO like)
Gene: Protein-coding gene on chromosome 5 (148,221,650 to 148,243,580, forward strand). Ensembl gene ENSG00000248109.
Gene Ontology:
Cellular component: endoplasmic reticulum lumen
Homologues: Orthologues: chimpanzee MARCOL (98% identical), dog MARCOL (46% identical), mouse Marcol (45% identical), rat Gm37797 (42% identical).